FGA (fibrinogen alpha chain)
Description:
Cleaved by the protease thrombin to yield monomers which, together with fibrinogen beta (FGB) and fibrinogen gamma (FGG), polymerize to form an insoluble fibrin matrix. Fibrin has a major function in hemostasis as one of the primary components of blood clots. In addition, functions during the early stages of wound repair to stabilize the lesion and guide cell migration during re-epithelialization. Was originally thought to be essential for platelet aggregation, based on in vitro studies using anticoagulated blood. However, subsequent studies have shown that it is not absolutely required for thrombus formation in vivo. Enhances expression of SELP in activated platelets via an ITGB3-dependent pathway. Maternal fibrinogen is essential for successful pregnancy. Fibrin deposition is also associated with infection, where it protects against IFNG-mediated hemorrhage. May also facilitate the immune response via both innate and T-cell mediated pathways.
Synonyms: AMYLD2; Fib2
Tractability: Small molecule: a structure with a bound ligand is known; it has a high-quality binding pocket. Antibody: UniProt places it where antibodies can reach, with high confidence; its Gene Ontology location is reachable by antibodies, with high confidence; UniProt predicts a signal peptide or a membrane-spanning region. PROTAC: its protein half-life has been measured. Other modalities: an approved drug acts on it.
Gene: Protein-coding gene on chromosome 4 (154,583,126 to 154,590,745, reverse strand). Ensembl gene ENSG00000171560.
Subcellular location: Secreted
Subcellular location (Human Protein Atlas): Endoplasmic reticulum; Predicted to be secreted
Pathways (Reactome):
Disease: Aggregated β-amyloid interacts with fibrinogen; IRAK4 deficiency (TLR2/4); MyD88 deficiency (TLR2/4); Paradoxical activation of RAF signaling by kinase inactive BRAF; Signaling by BRAF and RAF1 fusions; Signaling by RAF1 mutants; Signaling by high-kinase activity BRAF mutants; Signaling by moderate kinase activity BRAF mutants; Signaling downstream of RAS mutants
Signal Transduction: GRB2:SOS provides linkage to MAPK signaling for Integrins; Integrin signaling; MAP2K and MAPK activation; p130Cas linkage to MAPK signaling for integrins
Immune System: ER-Phagosome pathway; MyD88:MAL(TIRAP) cascade initiated on plasma membrane; Regulation of TLR by endogenous ligand
Metabolism of proteins: Amyloid fiber formation; Post-translational protein phosphorylation; Regulation of Insulin-like Growth Factor (IGF) transport and uptake by Insulin-like Growth Factor Binding Proteins (IGFBPs)
Hemostasis: Fibrin formation; Platelet degranulation
Extracellular matrix organization: Integrin cell surface interactions
Gene Ontology:
Molecular function: cell adhesion molecule binding; extracellular matrix structural constituent; protein binding; signaling receptor binding; structural molecule activity; protein-macromolecule adaptor activity
Biological process: blood coagulation, common pathway; blood coagulation, fibrin clot formation; cell-matrix adhesion; fibrinolysis; induction of bacterial agglutination; negative regulation of endothelial cell apoptotic process; negative regulation of extrinsic apoptotic signaling pathway via death domain receptors; plasminogen activation; platelet aggregation; positive regulation of ERK1 and ERK2 cascade; positive regulation of exocytosis; positive regulation of heterotypic cell-cell adhesion; positive regulation of peptide hormone secretion; positive regulation of protein secretion; positive regulation of vasoconstriction; protein polymerization; protein-containing complex assembly; response to calcium ion; positive regulation of substrate adhesion-dependent cell spreading; blood coagulation; platelet activation
Cellular component: blood microparticle; cell surface; endoplasmic reticulum; external side of plasma membrane; extracellular exosome; extracellular matrix; extracellular region; extracellular vesicle; fibrinogen complex; platelet alpha granule; endoplasmic reticulum lumen; non-collagenous component of interstitial matrix; plasma membrane; platelet alpha granule lumen
Genetic constraint (gnomAD): Loss-of-function variants: 16 observed, 16.14 expected, observed/expected ratio (o/e) 0.99, 90% interval 0.67 to 1.5. The upper end of that interval is the gene's LOEUF score, 1.5, which puts it in group 6 of 6, group 1 being the genes least tolerant of losing a copy. Missense variants: 730 observed, 769.95 expected, observed/expected ratio (o/e) 0.95, 90% interval 0.89 to 1.01. Synonymous variants: 286 observed, 274.39 expected, observed/expected ratio (o/e) 1.04, 90% interval 0.95 to 1.15.
Gene-disease validity (ClinGen):
ClinGen rates the evidence that FGA causes each of these diseases.
congenital fibrinogen deficiency (semidominant): Definitive. Congenital deficiencies of fibrinogen are coagulation disorders characterized by bleeding symptoms ranging from mild to severe resulting from reduced quantity and/or quality of circulating fibrinogen.
Homologues: Orthologues: zebrafish angptl2a (15% identical). Paralogues in human: ANGPTL2 (14% identical), TNC (13% identical), TNXB (11% identical), TNR (10% identical), FN1 (9% identical), TNN (8% identical), ANGPTL1 (6% identical), ANGPT1 (5% identical), ANGPT2 (5% identical), FGB (5% identical), ANGPTL3 (5% identical), ANGPTL6 (5% identical), and 13 more.
Diseases named in the same sentence as FGA in open-access papers:
FGA is named in the same sentence as 141 diseases in open-access papers, as found by Europe PMC text mining. Sharing a sentence is not in itself a finding about the gene and the disease. The quoted sentences say what the papers report.
COVID-19 (16 papers, 2020 to 2025). A disease caused by infection with severe acute respiratory syndrome coronavirus 2. "Following infection with a pseudotyped SARS-CoV-2 virus and live SARS-CoV-2, RNA-Seq and qPCR analyses revealed significant upregulation of fibrinogen genes (FGA, FGG), which are associated with severe COVID-19." (PMID 41453867, 2025). "Clusters A to C contain proteins with lower levels in COVID-19 convalescents, e.g. proteins functioning in cell adhesion and platelet degranulation (e.g. fibrinogen A (FGA), VWF), and innate immunity/the complement system (e.g. C1R, C1S, C1QA, C1QC, and GGH)." (PMID 38396092, 2024). "Several altered proteins in the serum of COVID-19 positive asymptomatic donors (FGA, SERPINA1, THBS1) and moreover, in CACs treated with these serum factors (HSPA5, FN1), have been associated with platelet aggregation and coagulation problems." (PMID 35397534, 2022). "Our data also showed increased levels of fibrinogen alpha, beta, and gamma chains (FGA, FGB, and FGG) in PLWH with COVID-19 compared to those in HCs." (PMID 40568587, 2025). "Plasma proteins including AAT, ABO, APP, FGA, HPX, ITIH4, PON and others showed similar or higher observation frequency in NHP compared to COVID-19." (PMID 37031181, 2023). "In the protein combination, 4 proteins including F11, F9, FGA and FGG are involved in the blood coagulation cascade, and all of them were higher expressed in COVID-19-children than those in healthy children or COVID-19-adults." (PMID 34335977, 2021). "In our results, F11, F9, FGG, FGA, SERPINA5, SERPINC1, and SERPINF2 are involved in the coagulation cascade, and significantly higher expressed in COVID-19-children compared with COVID-19-adults." (PMID 34335977, 2021). "However, the observation frequency of CRP, AAT, FGA, S100, SAA1 and others was often greater in ICU-ARDs or COVID-19 compared to normals, therefore these proteins were not specific markers of COVID-19 infection but rather reflected lung damage." (PMID 37031181, 2023).
gastric cancer (13 papers, 2014 to 2025). A primary or metastatic malignant neoplasm involving the stomach. "Elevated abundance of FGA and FpA in serum has been observed in patients with inflammation-associated diseases including systemic lupus erythematosus, Crohn’s disease, ischemic heart disease and gastric cancer." (PMID 31160890, 2019). "have revealed FGA as an attractive target for evaluating prognosis in gastric cancer by using DNA microarray analysis." (PMID 36338720, 2022). "Previous studies indicate that the serum level of FGA is upregulated in many tumors, such as gastric cancer, breast cancer, nasopharyngeal carcinoma, acute lymphocytic leukemia, esophageal squamous cell carcinoma, and renal cell cancer." (PMID 31998645, 2019). "Furthermore, FGA was found to be decreased in gastric cancer tissues and cell lines; its low expression is associated with a favorable prognosis." (PMID 39940778, 2025). "Moreover, the MSLN, SPP1, THBS2, SPARC, FN1, IGFBP7, VCAN were up-regulated in gastric carcinoma samples, while FGA was down-regulated." (PMID 36842141, 2023). "Various fibrinogen alpha chain and fibrinopeptide A fragments have been detected in hepatocellular, ovarian, urothelial and gastric cancers, although the m/z 5805.0 fragment has not been identified previously." (PMID 24495412, 2014). "Gastric cancer patients with high expression levels of FN1 (HR = 1.54, P < 0.05), MAC25 (HR = 1.48, P < 0.05), THBS2 (HR = 1.55, P < 0.05), VCAN (HR = 1.32, P = 0.0031), SPARC (HR = 1.42, P < 0.05), MSLN (HR = 1.28, P = 0.0066), and FGA (HR = 1.37, P < 0.05) had shorter survival time." (PMID 36842141, 2023). "However, APOA2, NTRK2, and FGA are oncogenes in PDAC, glioblastoma, and gastric cancer." (PMID 31143705, 2019).
afibrinogenemia (10 papers, 2016 to 2025). "The FGA gene is most often involved in afibrinogenemia and loss of function variants were most frequent." (PMID 34356081, 2021). "Afibrinogenemic puppies were homozygous mutant for the FGA rs1152388481 variant supporting that this mutation is responsible for afibrinogenemia." (PMID 34356081, 2021). "Mutations of FGA have been linked to coagulation pathologies including afibrinogenemia (OMIM:202400) and dysfibrinogenemia/hypodysfibrinogenemia (OMIM:616004), which can result in miscarriage." (PMID 34925444, 2021). "The present data provide evidence for a novel FGA truncating frameshift mutation that is very likely to explain the cases of severe bleeding due to afibrinogenemia in a Dachshund family." (PMID 34356081, 2021). "FGA mutations, especially drastic biallelic variants, have been associated with afibrinogenemia, a rare bleeding disorder." (PMID 29016666, 2017). "The patient with afibrinogenemia exhibited a homozygous mutation in FGA: c.1483dup.M495Nfs*18." (PMID 39805289, 2025). "Validation of the FGA rs1152388481 variant in the pedigree of the cases, in dogs of all nine Dachshund breeds and a large panel of dogs from other breeds, gave confidence that this FGA-associated mutation is responsible for afibrinogenemia in these Dachshunds." (PMID 34356081, 2021). "This deletion has been reported in at least eight afibrinogenemic patients, and, together with other two gross deletions that are described in the FGA gene (i.e., a 15-kb and a 4.1-kb deletion), account for ~9% of all cases of afibrinogenemia characterized by mutations in FGA." (PMID 29240685, 2017). "The missense mutations causing quantitative fibrinogen deficiency (including both hypofibrinogenemia and afibrinogenemia) can be located in all three fibrinogen genes; subsequently, missense mutations in the FGA gene have also been described, both in afibrinogenemic and hypofibrinogenemic patients." (PMID 29286337, 2017). "Autosomal-recessive fibrinogen deficiency appears to be virtually absent in Ashkenazi Jews (no mutations found in FGA and FGB; prevalence for FGG of 1.64 per 106 individuals), whereas, non-Finnish Europeans have a predicted exceptional rate of 23.05 per 106 individuals for the sole FGG gene." (PMID 29240685, 2017). "FGA or FGG KO in mice leads to precluded assembly of functional circulating FG protein, resulting in congenital hypofibrinogenemia and afibrinogenemia as well as related atherosclerosis, colitis, multiple sclerosis and pregnancy failure." (PMID 39168965, 2024). "Subnetwork 2 showed potential functional relationships between proteins FGB, FGA, APOA1, and afibrinogenemia congenital, amyloidosis familial visceral, and hypoalphalipoproteinemia." (PMID 30532734, 2018). "In this study, we performed genetic analysis of FGA, FGB and FGG genes, coagulation tests and rotational thromboelastometry in two families with quantitative congenital fibrinogen disorders (afibrinogenemia and hypofibrinogenemia)." (PMID 29286337, 2017).
breast carcinoma (9 papers, 2006 to 2025). "The expression data of ECM fiber-encoding genes (e.g., COL1A1, COL1A2, FGA, FGB, FGG, ELN, FN1, and VTN) from 1358 patients with breast cancer were used for Kaplan–Meier overall survival analysis." (PMID 37369642, 2023). "According to the xiantao database, COL1A2, COL3A1, FGA, LUM, APOA1, APOH, and COL5A2 were more highly expressed in breast cancer than in normal tissues (p < 0.05), while the opposite pattern was seen for ALB and FBN1 (p < 0.05)." (PMID 37079213, 2023). "For gene markers in HER2 breast cancers, possible targeting of individual clusters with PLAT, ICAM1, and FGA is observed." (PMID 36598637, 2023).
thrombosis (9 papers, 2014 to 2026). "Among 5 variants previously reported in patients with thrombosis, FGA p.Arg35Cys, FGG p.Arg301Cys, and FGG p.Asp344Gly showed markedly prolonged T lysis compared with the normal reference range, indicating altered clot formation-lysis kinetics." (PMID 42027313, 2026). "For instance, the p.Arg554Cys mutations in the FGA gene, the p.Ala68Thr mutation in the FGB gene, and the p.Asp364Val mutation in the FGG gene have all been linked to thrombosis." (PMID 41030265, 2025). "Proteins related to venous thrombosis and blood coagulation, such as Coagulation factor VII (F7) and Fibrinogen alpha chain (FGA), were upregulated in the ZIKV group." (PMID 33312964, 2020). "Coagulation-related factors, such as F2, SERPIND1, SERPINF2, SERPINA3, FGA, FGB, and FGG, are also downregulated, leading to coagulation dysfunction in the body, which is not conducive to post-exercise recovery and can even lead to thrombosis in severe cases." (PMID 40646880, 2025). "Similarly to VITT02, a VUS in the FGA gene was also detected in VITT06 patient, also exhibiting both venous thrombosis and stroke." (PMID 39035772, 2024).
dysfibrinogenemia (8 papers, 2015 to 2022). "Dysfibrinogenemia is usually associated with AD inheritance with two hotspots described, namely FGA p.Arg35 and FGG p.Arg301." (PMID 33807613, 2021). "FGA heterozygous missense mutations have been identified in patients affected by dysfibrinogenemia, a blood disorder having an unpredictable clinical phenotype due to abnormal fibrinogen quality." (PMID 29016666, 2017). "Laboratories, where performance of TT and RT is not part of routine coagulation screening, may misdiagnose certain types of fibrinogen abnormalities, like the dysfibrinogenemia caused by FGA p.Arg35Cys/His and p.Arg38Ser mutations, or the FGG p.Arg301His mutation." (PMID 33807613, 2021). "Concerning fibrinogen abnormalities, most of our patients were carriers of the frequent mutations in FGA exon 2 (p.Arg35Cys and p.Arg35His) or in FGG exon 8 (p.Arg301His), which are responsible for more than 80% of all variants in dysfibrinogenemia." (PMID 33807613, 2021).
Hypofibrinogenemia (8 papers, 2016 to 2024). Decreased concentration of fibrinogen in the blood. "In conclusion, the presented case was characterized by spontaneous bleeding during childhood caused by inherited hypofibrinogenemia due to heterozygous mutation in the FGA gene." (PMID 35207353, 2022). "Hypofibrinogenemia can be considered the phenotypic expression of heterozygous loss of function mutations occurring within one of the three fibrinogen genes (FGA, FGB, and FGG)." (PMID 33322159, 2020). "Mutations in any of the Fibrinogen gene (FGA, FGB, FGG) can result in hypofibrinogenemia." (PMID 34071368, 2021). "Apparent exceptions are missense mutations or a single large deletion in the fibrinogen gamma chains and in a single case report a missense mutation of the FGA gene previously documented to be associated with dysfibrinogenemia but not with hypofibrinogenemia." (PMID 34071368, 2021). "We have sequenced all exons of the FGA, FGB, and FGG genes using the DNA isolated from the peripheral blood in two unrelated probands with mild hypofibrinogenemia." (PMID 33322159, 2020).
liver cancer (8 papers, 2013 to 2025). An epithelial or non-epithelial malignant neoplasm that arises from the liver. "By constructing both FGA gene knockout and overexpression cell models, we demonstrated that overexpressing FGA inhibited migration and invasion of liver cancer cells through Transwell migration/invasion and wound healing assays." (PMID 39227068, 2024). "We also identified a proliferative cluster, which mainly consisted of proliferating T cells and a large cluster of HCC cancer cells (40%) expressing both genes associated with normal liver function (ALB, HP, FGA, FGB) and liver cancer (AFP, SPINK1, GPC3, AKR1C1)." (PMID 38030622, 2023). "It has been reported that the non-coding sequences between FGA and fibrinogen gamma (FGB) are active in liver cancer cells." (PMID 39227068, 2024). "Several cfRNAs specific to liver cancer are genes known to be specifically expressed in the liver (TF, HRG, CP, and FGA)." (PMID 35816095, 2022). "Thus, FGA, FGB, FGG and FGL1 could be important direct target genes of FOXA1 that are involved in EMT of lung and liver cancer specifically." (PMID 24093963, 2013).
lung carcinoma (7 papers, 2013 to 2025). "FGA encodes the alpha subunit of the coagulation factor fibrinogen, and downregulation of FGA seems to be associated with poor prognosis in human lung cancer." (PMID 33718182, 2021). "In this study, we examined the protein expression of the FGA gene in normal lung tissues and lung cancer tissues using this database, and the results suggest that FGA is decreased in normal tissue and increased in lung cancer tissues." (PMID 40861466, 2025). "FGA expression was the highest in the hepatocellular carcinoma cell line HepG2, more than in lung cancer cell lines such as A549 and H1299." (PMID 35885017, 2022). "It was found that the knockout of FGA promotes tumor growth and metastasis, suggesting the role of FGA as a suppressor for tumor growth and metastasis in the lung cancer." (PMID 35885017, 2022). "In addition, FGA knockdown with lentivirus-mediated shRNA interference enhanced the resistance of lung cancer cells to cisplatin and gemcitabine." (PMID 39940778, 2025). "Increased expression of FGA may also be favorable in lung cancer where it was suggested to have a suppressive role inhibiting tumor growth and metastasis in human lung adenocarcinoma." (PMID 35885017, 2022). "There was a strong correlation between the survival time of individuals with lung cancer and 7 genes (CLEC3B, AOC3, HBB, CAT, SEPP1, FGA, and ORM1, P<0.05)." (PMID 40496615, 2025). "A total of 6 genes (LYVE1, CLEC3B, FGA, AOC3, HYDIN, and HBB) exhibited differential expressions in the plasma of LUSC and the area of the lesion in lung cancer (including LUAD and LUSC)." (PMID 40496615, 2025). "FGA, FGB, FGG and FGL1 were downregulated during EMT of lung cancer and were mapped to the GO term ‘Fibrinogen complex’." (PMID 24093963, 2013).